SMARCA2 (SWI/SNF related BAF chromatin remodeling complex subunit ATPase 2)
Diseases named in the same sentence as SMARCA2 in open-access papers (continued):
Sharing a sentence is not in itself a finding about the gene and the disease.
thyroid cancer (3 papers, 2020 to 2025). "Beside the role of FAM129A in thyroid cancer, the loss of SMARCA2 was also found to be associated with thyroid cancer, particularly with anaplastic thyroid cancer." (PMID 32019955, 2020). "If this holds true, then SMARCA2/FAM129A could be potential biomarkers for stratifying HT patients who maybe of higher risk of developing thyroid cancer." (PMID 32019955, 2020). "To confirm that SETMAR promotes thyroid cancer differentiation by regulating SMARCA2, we transfected shRNAs against SMARCA2 into SETMAR‐overexpressing ATC cells." (PMID 38900084, 2024). "To further explore how SETMAR‐regulated SMARCA2 plays a role in promoting differentiation in thyroid cancer, we employed the CRISPRa technique to overexpress SMARCA2 in ATC cells by activating its endogenous promoter." (PMID 38900084, 2024). "Therefore, SETMAR-activated SMARCA2 enhances chromatin accessibility for the active expression of thyroid differentiation transcription factors through chromatin remodeling to regulate thyroid cancer differentiation." (PMID 40819127, 2025). "Our study revealed that SMARCA2 could regulate the chromatin accessibility of key thyroid lineage transcription factors through chromatin remodeling, thus regulating thyroid cancer differentiation." (PMID 38900084, 2024). "We found that overexpression of SETMAR could promote the protein and mRNA expression of SMARCA2 in thyroid cancer cells, while inhibition of SETMAR had the opposite effect." (PMID 38900084, 2024). "Additionally, SMARCA2 also attenuated the proliferative potential of thyroid cancer cells in vivo." (PMID 38900084, 2024). "Finally, we examined the expression pattern of SMARCA2 in thyroid cancer." (PMID 38900084, 2024).
carcinoids (2 papers, 2017 to 2021). "No genetic alteration was exclusive to a specific LNET subtype, but the differences between carcinoids and carcinomas reside in the prevalence rates of the most frequently mutated genes, with the exception of SMARCA2, which was altered in LCNECs only (p = 0.011)." (PMID 27873319, 2017).
chronic myelogenous leukemia (2 papers, 2017 to 2024). "The anti-cancer efficacy of SMARCA2/4 degraders was next evaluated withex vivo patient-derived cells from cases of plasma cellleukemia (PCL), an aggressive form of MM, and chronic myelogenous leukemia(CML)." (PMID 39029462, 2024). "The analysis identified six significant gene sets at the diabetes studies and the combined datasets, including “UV response”, “chronic myelogenous leukemia”, “KLF1 targets”, “SMARCA2 targets”, “Alzheimer’s disease” and “stromal stem cells”." (PMID 28117714, 2017).
developmental delay (2 papers, 2019 to 2026). "The diagnosis was based on clinical presentation, such as attention deficit hyperactivity disorder, cognitive delay, and characteristic craniofacial features, and confirmed by the presence of a de novo mutation in the SMARCA2 gene through whole-exome sequencing." (PMID 41497020, 2026).
endometrial undifferentiated carcinoma (2 papers, 2022 to 2025). A primary carcinoma of the endometrium characterized by the presence of malignant cells that lack evidence of differentiation. "SMARCA2/BRM and BRG1/SMARCA4 are lost in approximately one-third of endometrial undifferentiated carcinomas." (PMID 35633893, 2022).
hypertrichosis (2 papers, 2019 to 2021). Excessive hair growth anywhere on the body. "Subject 12, with the SMARCA2 variant, displayed typical features of NCBRS (e.g., coarse face with hypertrichosis, thick eyebrows, thick lips, long eyelashes, nail hypoplasia, and microcephaly), but did not have prominent interphalangeal joints." (PMID 34706719, 2021).
large cell carcinoma (2 papers, 2021 to 2022). A malignant epithelial neoplasm composed of large, atypical cells. "Of the few large cell carcinomas investigated in that study, 2/6 cases (33%) had a loss of SMARCA2." (PMID 33506327, 2021).
liver cancer (2 papers, 2017 to 2025). An epithelial or non-epithelial malignant neoplasm that arises from the liver. "Indeed, lnc-SMARCA2 has been previously implicated in liver cancer as a regulator of the SWI/SNF chromatin modulator complex." (PMID 41164329, 2025).
lymphoma (2 papers, 2015 to 2025). A malignant (clonal) proliferation of B- lymphocytes or T- lymphocytes which involves the lymph nodes, bone marrow and/or extranodal sites. "We observed that mutations were frequent in malignant lymphoma (Germinal center B-cell derived lymphomas) for the BAF ATPase SMARCA2 (18%) and auxiliary subunits ARID1A (18%), ARIDB (32%), ARID2 (18%), and DPF3 (23%), and other subunits were also mutated at lower frequencies." (PMID 25789315, 2015).
microcephaly (2 papers, 2021 to 2023). A congenital or acquired developmental disorder in which the circumference of the head is smaller than normal for the person's age and sex. "Duplication of the 9p24.3p13.1 region involving the SMARCA2 gene cause Nicolaides–Baraitser syndrome, which may be associated with DD, ID, microcephaly, and short stature." (PMID 37189911, 2023).
mucinous adenocarcinoma (2 papers, 2021 to 2022). An invasive adenocarcinoma composed of malignant glandular cells which contain intracytoplasmic mucin. "They reported that SMARCA2 expression was severely decreased (>50% of tumor cells were negative) in 42% (37/89) of GCs and deficient SMARCA2 expression was usually in tubular and papillary adenocarcinoma but not in signet-ring cell or mucinous carcinoma." (PMID 33481850, 2021). "In our study, among the 90 mucinous adenocarcinoma cases, the deletion ratios of SMARCA4, SMARCA2, and ARID1A subunits were 6.7%, 5.6%, and 4.5%, respectively." (PMID 35289322, 2022).
myelodysplastic syndrome (2 papers, 2023 to 2024). A clonal hematopoietic disorder characterized by dysplasia and ineffective hematopoiesis in one or more of the hematopoietic cell lines. "Moreover, sequencing studies carried out on AML and/or myelodysplastic syndromes (MDS) have found recurrent deleterious mutations in SWI/SNF genes including ARID2, ARID1A and ARID1B, SMARCA2, and SMARCA4." (PMID 36941700, 2023).
rhabdomyosarcoma (2 papers, 2025). A rare aggressive malignant mesenchymal neoplasm arising from skeletal muscle. "The SMARCA4/SMARCA2 PROTAC, ACBI1, is also reported to have some efficacy in preclinical rhabdomyosarcoma models." (PMID 40983796, 2025).
undifferentiated carcinoma (2 papers, 2021 to 2022). A usually aggressive malignant epithelial neoplasm composed of atypical cells which do not display evidence of glandular, squamous, or transitional cell differentiation. "This is the first reported case of an undifferentiated carcinoma with rhabdoid features in the gallbladder carrying a POLE mutation and SWI/SNF-deficiency of PBRM1 and SMARCA2." (PMID 34118935, 2021). "Immunohistochemical loss of SMARCA2 and SMARCA4 can occur simultaneously or independently, and undifferentiated carcinomas with SMARCA2 loss without SMARCA4 loss have also been reported, suggesting that SMARCA2 loss was also involved in the process of tumor dedifferentiation." (PMID 36464671, 2022). "In this study, SMARCA2 was the most frequently lost subunit, while it was not thoroughly investigated in undifferentiated carcinomas compared with SMARCA4." (PMID 36464671, 2022).
acute leukemia (1 paper, 2019). A clonal (malignant) hematopoietic disorder with an acute onset, affecting the bone marrow and the peripheral blood. "A critical requirement on SMARCA4 in promoting MYC-dependent transcription has been described in SMARCA2-proficient acute leukemia cell models." (PMID 31406271, 2019).
alcohol abuse (1 paper, 2024). The use of alcoholic beverages to excess, either on individual occasions ("binge drinking") or as a regular practice.
alopecia (1 paper, 2025). Hair loss usually from the scalp. "The constellation of severe atopic dermatitis and progressive alopecia in this patient suggests that SMARCA2 dysfunction may compromise epidermal barrier integrity and hair‐follicle cycling, rendering affected children particularly susceptible to eczematous inflammation and telogen shift." (PMID 40881542, 2025).
anaplastic thyroid cancer (1 paper, 2024). "Based on our analysis of the single‐cell dataset, we observed a significant decrease in the expression of SMARCA2 in tumor cells, particularly in anaplastic thyroid cancer (ATC) cells, compared to that in normal thyroid follicular epithelial cells." (PMID 38900084, 2024).
brain cancer (1 paper, 2023). A primary or metastatic malignant neoplasm affecting the brain. "Whilst SMARCA2 inhibition has been demonstrated as a successful therapeutic strategy in SMARCA4-deficient cancer cell lines, its viability is yet to be confirmed in brain cancer cell lines where SMARCA4 is frequently inactivated." (PMID 37433987, 2023).
Burkitt lymphoma (1 paper, 2023). A rare form of malignant mature B-cell non-Hodgkin lymphoma. "In contrast to SMARCA2/4 and ARID1A/1B/2 genes, BCL7A seems to be specifically mutated in lymphomas that are either derived from or phenotypically similar to germinal center B cells, such as germinal center B cell-like (GCB) DLBCL, FL, Burkitt lymphoma (BL), and MM." (PMID 36810086, 2023).
carcinoma of the esophagus (1 paper, 2024). "Undifferentiated carcinoma of the esophagus with SMARCA4 and/or SMARCA2 deficiency is a rare tumor associated with a very poor prognosis." (PMID 38656564, 2024).
cardiomyopathy (1 paper, 2023). A disease of the heart muscle or myocardium proper. "Emerging data, however, indicate that depletion of Smarca4 levels in postnatal cardiomyocytes by adenoviral-based siRNA knockdown or dual genetic KO strategy with Smarca2 causes lethal cardiomyopathy in mice." (PMID 36656640, 2023).
chondrosarcoma (1 paper, 2023). A malignant cartilaginous matrix-producing mesenchymal neoplasm arising from the bone and soft tissue. "Olaparib decreased cell survival of CH2879 chondrosarcoma cells and the radiosensitivity was associated with mutations in homologous recombination repair genes, such as RAD50, SMARCA2, and NBN." (PMID 36768638, 2023).
chordoma (1 paper, 2025). Chordomas are rare malignant tumors arising from embryonic remnants of the notochord in axial skeleton. "Our findings of enrichments in SWI/SNF complex mutations, such as PBRM1, ARID1A, SETD2, and SMARCA2, indicate that epigenetic therapies may be effective in some chordoma cases." (PMID 39941902, 2025).
depression (1 paper, 2022). "In an investigation of bivariate analyses of genome-wide association study results relating to depression combined with MDD, BPD, and SCZ, the authors found that the SMARCA2 gene and the SWI/SNF gene set were enriched." (PMID 35444632, 2022).
esophageal cancer (1 paper, 2019). A primary or metastatic malignant neoplasm involving the esophagus. "We highlight the relevance of SMARCA4 as a drug target in esophageal cancer using an engineered ESCC cell model harboring a SMARCA4 allele amenable to targeted proteolysis and identify SMARCA4-dependent cell models with low or absent SMARCA2 expression from additional tumor types." (PMID 31406271, 2019).
Ewing sarcoma (1 paper, 2023). A small round cell tumor that lacks morphologic, immunohistochemical, and electron microscopic evidence of neuroectodermal differentiation. "In additional, several other non-DNA binding transcriptional regulators are present among all Supertargets: a component of the cohesion complex STAG1 (Ewing sarcoma), SMARCA2 (lung) and SMARCAL1 (osteosarcoma)." (PMID 37297004, 2023).
granulosa cell tumor (1 paper, 2023). A slow-growing, malignant tumor, characterize by the presence of granulosa-like cells and Call-Exner bodies, that is almost always found in the ovary. "It is worth noting that COV434 cells, which were formerly classified as a juvenile granulosa cell tumor, have now been reclassified as SCCOHT, based on its SMARCA4 mutation and lack of SMARCA2 expression." (PMID 37535222, 2023).
gynecologic cancers (1 paper, 2025). "The loss of SMARCA4 (BRG1) and SMARCA2 (BRM) protein is pathognomonic for SCCOHT amongst other gynecologic cancers and histopathologic mimics." (PMID 39906560, 2025).
heart failure (1 paper, 2024). Inability of the heart to pump blood at an adequate rate to meet tissue metabolic requirements. "After intersecting the results of the three algorithms, we obtained four down-regulated key aging genes in heart failure, namely BCL6, EIF4EBP1, MEIS2, and SMARCA2." (PMID 38686376, 2024).
Hypoglycemia (1 paper, 2023). A decreased concentration of glucose in the blood. "SMARCA2 and RFX3 were proposed as potential candidates for the hypoglycemia, but no experimental evidence has been provided." (PMID 37065762, 2023).
lung neuroendocrine tumors (1 paper, 2025). "The literature indicates that approximately 3%-7% of lung neuroendocrine tumors harbor SMARCA2 and SMARCA4 mutations." (PMID 40661782, 2025).
lung sarcomatoid carcinoma (1 paper, 2023). A rare, aggressive, poorly differentiated, non-small cell lung carcinoma characterized by the presence of a sarcomatoid component often associated with giant cell differentiation. "Our aim was to determine the features of SMARCA4 and SMARCA2 deficiency in lung sarcomatoid carcinomas." (PMID 36178285, 2023). "The aim of our study was to examine SMARCA4 and SMARCA2 profiles in sarcomatoid carcinomas of the lung." (PMID 36178285, 2023).
myoclonic astatic epilepsy (1 paper, 2017). "We report a de novo SMARCA2 missense mutation discovered on exome sequencing in a patient with myoclonic astatic epilepsy, leading to reassessment and identification of Nicolaides–Baraitser syndrome." (PMID 27665729, 2017).
myopia (1 paper, 2026). "Our meta-analysis identified seven novel suggestive loci associated with myopia progression, including FSTL5 on 4q32.2, SMARCA2 on 9p24.3, CCDC3 on 10p13, GALNT6/ACVR1B on 12q13.13, CRY1 on 12q23.3, ULK2 on 17p11.2, and MYL4/EFCAB13-DT on 17q21.32." (PMID 42094695, 2026).
nasopharyngeal carcinoma (1 paper, 2025). A carcinoma arising from the nasopharyngeal epithelium. "Furthermore, we found that the core genes of the nasopharyngeal carcinoma radiosensitivity signature (NPC-RSS), namely SMARCA2, DMC1, CD9, PSG4, and KNG1, had significant correlations with previously published genes related to radiosensitization." (PMID 40530955, 2025).
non-melanoma skin carcinoma (1 paper, 2019). "Alterations in BRM expression seem to be important for the non-melanoma skin cancer (NMSC) development, and in this case, the role of SMARCA2 as a susceptibility gene is strongly pronouncing." (PMID 31722744, 2019).
soft tissue tumors (1 paper, 2024). "In the sinonasal tract, deficiencies of the subunits SMARCB1/INI1, SMARCA4/BRG1, and SMARCA2 have been noted in carcinomas, adenocarcinomas, and soft tissue tumors with a distinctive high-grade morphology and a fatal prognosis." (PMID 39590317, 2024).
tumor (166 papers, 2011 to 2026). "delineated divergent prognostic associations: SMARCA4 overexpression correlates with tumour invasiveness, whereas elevated SMARCA2 expression marks benign differentiation states—a dichotomy particularly pronounced in HCC." (PMID 41578412, 2026). "SMD‐3040 is a highly efficient and selective SMARCA2 degrader (>80‐fold selectivity) with preferential activity in SMARCA4‐deficient tumour cells." (PMID 41537447, 2026). "The report provides novel insights into the distinct roles of SMARCA2 and SMARCA4 in LUAD pathogenesis, highlighting the immunosuppressive tumor microenvironment associated with SMARCA2 deficiency." (PMID 40453096, 2025). "The absence of Claudin-4 expression further supported the diagnosis of a mesenteric SMARCA2-deficient yet SMARCA4-preserved undifferentiated tumor." (PMID 40012963, 2025). "HDACi can restore SMARCA2 expression in a variety of SMARCA2-deficient cell lines, thereby inhibiting tumor cells proliferation." (PMID 38347129, 2024). "HDACi have been shown to restore SMARCA2 expression in various SMARCA2-deficient tumors, reduce tumor cell growth, enhance sensitivity to cisplatin, and restore sensitivity to PD-1 inhibitors." (PMID 38903719, 2024). "On the other hand, in pancreatic cancer, the upregulation of SMARCA2 associates with disease progression, being significantly positively correlated with patients’ poor survival, larger tumor size, metastases, lymphatic invasion, and stage IV disease." (PMID 36674511, 2023). "Among them, global transcription activator, encoded by SMARCA2, was reported to have a potential tumor suppressor activity in cancer." (PMID 34209254, 2021). "Both subunits have been shown to be mutually exclusive subunits in SWI/SNF complexes, and survival of SMARCA2-mutated cells depends on the residual SMARCA4-containing complex activity in specific tumor entities." (PMID 33227989, 2020). "The genes encoding the ATPase of the chromatin remodeling SW1/SNF complexes SMARCA4 and the alternative SMARCA2 are usually mutated or silenced in tumors, suggesting a role as tumor suppressor." (PMID 33218162, 2020). "Some data indicated SMARCA2/BRM as a tumour suppressor or tumour susceptibility gene, whereas overexpression of BRM caused cancer resistance for chemotherapy leading to cancer progression indicating its promoting role." (PMID 31722744, 2019). "In tumours with SMARCA2 depletion caused by PRC2-driven methylation, usage of EZH2 inhibitors seems to be a promising therapy." (PMID 31722744, 2019). "In BRM-deficient ccRCC tumours almost 90% cases displayed genetic alterations in the SMARCA2 gene, such as mutations, promoter methylation or chromosomal aberrations." (PMID 31722744, 2019). "Tumor #7 from the stage 1 group provided an example: the SMARCA2 loss was a truncal event, PBRM1 loss was a branch event, while ARID1A and SMARCA4 losses were branch events that happened even later." (PMID 28445125, 2017). "For instance, tumor sequencing has unveiled some of these functional differences: SMARCA2 inactivation by mutation is infrequent in tumor development; however, SMARCA4 has been found mutated in primary tumors and cancer cell lines." (PMID 25391308, 2014). "In a similar lung model, heterozygous or homozygous loss of SMARCA2 led to increased tumor formation." (PMID 24622842, 2014). "While SMARCA2 exhibits low mutational frequency in malignancies, its transcriptional repression is a recurrent feature across multiple cancer cell lines and primary tumours." (PMID 41578412, 2026). "Moreover, once-daily treatment with CP-C27 led to marked suppression of tumor growth in SMARCA4/SMARCA2-deficient DMS114 and SS18–SSX fusion Fuji xenograft models, again with no adverse effect on the body weight of mice." (PMID 39625239, 2025). "Furthermore, SMARCA2 is implicated in processes such as cell adhesion and cytokine response, which are tightly coupled to the interactions of tumor cells within the microenvironment." (PMID 40530955, 2025).